SYP (synaptophysin)
Diseases named in the same sentence as SYP in open-access papers (continued):
Sharing a sentence is not in itself a finding about the gene and the disease.
breast carcinoma (continued). "We have not been able to identify any prior investigations into the expression of synaptophysin and chromogranin in MMTV positive human breast cancers or MMTV positive mouse mammary tumours." (PMID 28523075, 2017). "The expression of synaptophysin and chromogranin in MMTV positive mouse mammary tumours were all positive (7 of 7 specimens – 100% positive)." (PMID 28523075, 2017). "The expression of synaptophysin and chromogranin in MMTV positive mouse mammary tumors were all positive (7 of 7 specimens – 100% positive)." (PMID 28523075, 2017). "As an additional result, we demonstrated that VGF a recently described NE marker showing similarities with members of the secretogranin/chromogranin family is also expressed in NE breast cancers producing CHGA and/or SYP." (PMID 24277232, 2014). "Over-expression of one or more NE marker (CHGA and/or SYP and/or VGF) characterizes a significant fraction (approximately 10 %) of infiltrative breast cancers." (PMID 24277232, 2014). "Although cutaneous metastasis from a radiologically undetectable breast cancer cannot be completely ruled out, it appears unlikely given the different histomorphology of the 2 tumors and the absence of PR and synaptophysin expression in the breast cancer." (PMID 41143220, 2025). "The synaptophysin and chromogranin positive MMTV positive human breast cancers are characterised by intensely stained nuclei which occupy most of the cell, the cells are mostly round and regular in size and are clumped together without glandular acini or lumen." (PMID 28523075, 2017). "To explore this hypothesis we investigated by immunohistochemistry, the expression of synaptophysin and chromogranin in a series of MMTV positive human breast cancers and MMTV positive mouse mammary tumours." (PMID 28523075, 2017). "Here we show that the expression of synaptophysin and chromogranin in MMTV positive breast cancers is not usually associated with human neuroendocrine breast cancers." (PMID 28523075, 2017). "The high prevalence of positive expression of synaptophysin and chromogranin in MMTV positive mouse mammary tumours and low expression of synaptophysin and chromogranin in MMTV positive human breast cancers indicates that MMTV is not usually associated with neuroendocrine human breast cancers." (PMID 28523075, 2017). "Currently, NE differentiation in breast cancers has been assessed by immunohistochemical procedures detecting “general” NE markers such as chromogranin A (CHGA) and synaptophysin (SYP), and elucidation of specific hormonal peptides has been absent or unproductive." (PMID 24277232, 2014). "However it must be emphasised that the histological characteristics of MMTV positive and synaptophysin and chromogranin negative human breast cancers are also similar to MMTV positive mouse mammary tumours." (PMID 28523075, 2017). "However, the substantial differences in the expression of synaptophysin and chromogranin in MMTV positive human breast cancer and MMTV positive mouse mammary tumours indicate that MMTV is not usually associated with neuroendocrine human breast cancers." (PMID 28523075, 2017). "In our case, chromogranin A, synaptophysin, CD56, and TTF1 were not stained initially, and the diagnosis was triple negative primary bilateral breast cancer." (PMID 39292386, 2024).
glioma (15 papers, 2008 to 2025). A benign or malignant brain and spinal cord tumor that arises from glial cells (astrocytes, oligodendrocytes, ependymal cells). "This review explores the diagnostic significance of vimentin, synaptophysin, and H3K27me, highlighting their role in glioma classification and their potential utility in differentiating oligodendrogliomas from DMGs." (PMID 40937216, 2025). "Despite some variability, synaptophysin remains a practical diagnostic tool in differentiating glioma subtypes when used as a part of a multi-marker panel." (PMID 40937216, 2025). "Vimentin, synaptophysin, and H3K27me expression patterns offer practical, cost-effective surrogate tools to enhance diagnostic accuracy in glioma classification." (PMID 40937216, 2025). "Synaptophysin expression was associated with proneural subtype and vGlut1 expression, suggesting that most synapse-like structures in glioma are glutamatergic." (PMID 30297697, 2018). "Despite the promising clinical applications of vimentin, synaptophysin, and H3K27me, there remain several limitations and gaps in research that must be addressed to further optimize their use in glioma diagnostics and treatment planning." (PMID 40937216, 2025). "The presence of synaptophysin in gliomas suggests a degree of neuronal lineage differentiation, which is more commonly observed in oligodendrogliomas than in astrocytic gliomas." (PMID 40937216, 2025). "Among gliomas, oligodendrogliomas frequently express synaptophysin, indicating a degree of neuronal differentiation, while DMGs typically lack strong synaptophysin positivity." (PMID 40937216, 2025). "While synaptophysin is a valuable marker in glioma classification, it has limitations that must be considered when interpreting its expression." (PMID 40937216, 2025). "Vimentin's association with aggressive, mesenchymal-like transformation supports its utility in identifying high-grade gliomas such as DMGs, while synaptophysin expression points toward neuronal differentiation, favoring a diagnosis of oligodendroglioma." (PMID 40937216, 2025). "In gliomas, synaptophysin expression varies significantly across subtypes, reflecting differences in their lineage differentiation and molecular characteristics." (PMID 40937216, 2025). "This differential expression makes synaptophysin a useful surrogate marker for distinguishing oligodendrogliomas from other gliomas, particularly astrocytic tumors such as DMGs." (PMID 40937216, 2025). "In the absence of comprehensive molecular testing, immunohistochemical markers such as vimentin, synaptophysin, and H3K27me serve as valuable surrogate tools to differentiate between these glioma subtypes." (PMID 40937216, 2025). "The primary search string used was: ("vimentin" OR "synaptophysin" OR "H3K27me3" OR "H3K27M") AND ("oligodendroglioma" OR "diffuse midline glioma" OR "glioma classification" OR "brain tumor diagnosis")." (PMID 40937216, 2025). "Higher expression levels of RAB3A, SYP, CAMK2A, and GABRA1, as well as lower expression levels of TYROBP and VSIG4, in glioma patients were associated with improved OS and DFS." (PMID 36072978, 2022). "It is suggested that SYP can be a molecular index to judge the tumor grade and predict prognosis, especially for low-grade gliomas." (PMID 34136394, 2021). "In accordance with clinical work, synaptophysin (SYP) can be used as a predictor of disease progression and clinical prognosis of gliomas, especially low-grade gliomas." (PMID 34136394, 2021). "Based on the good predictive performance of the SYP gene in low-grade gliomas, preoperative MRI data of 124 patients with WHO grades II and III were downloaded from the TCGA database." (PMID 34136394, 2021). "Synaptophysin, the most commonly expressed neural marker, exists widely in a variety of lesions of primary central nervous system neoplasms, from gliomas to the lowest differentiated primitive neuroectodermal tumors." (PMID 34136394, 2021).
glioma (continued). "The expression results of SYP, which is a common index for the pathological diagnosis of glioma, are easy to obtain." (PMID 34136394, 2021). "This study aimed to explore the feasibility of applying a multiparametric magnetic resonance imaging (MRI) radiomics model composed of a convolutional neural network to predict the SYP gene expression in patients with glioma." (PMID 34136394, 2021). "Among patients with WHOIII gliomas, it was shown that the expression level of SYP was higher in patients with MGMT promoter methylation." (PMID 34136394, 2021). "In this study, we used a convolutional neural network (ConvNet) to build a radiomics model based on multiparametric magnetic resonance imaging (MRI) to predict SYP expression levels in patients with low-grade glioma." (PMID 34136394, 2021). "Positive immunoreaction of synaptophysin is in accordance with the reported nevronal elements in glial tumors." (PMID 22011735, 2011). "For example, tumors with high vimentin expression may be more responsive to therapies targeting tumor invasion and migration, while synaptophysin-positive gliomas could benefit from differentiation-inducing therapies." (PMID 40937216, 2025). "The integration of immunohistochemical (IHC) and molecular markers, such as vimentin, synaptophysin, and H3K27me, has significantly enhanced the ability to distinguish between different glioma subtypes, particularly oligodendrogliomas and diffuse midline gliomas (DMGs)." (PMID 40937216, 2025). "The role of vimentin in guiding therapy selection remains largely unexplored, and more research is needed to determine whether synaptophysin-positive gliomas have unique therapeutic vulnerabilities." (PMID 40937216, 2025). "After analyzing the sequencing data of 614 cases from TCGA, we found the expression level of SYP in the glioma to be correlated with the tumor grade and the survival rate of the patient, and that the expression level of SYP decreased with an increase in tumor grade." (PMID 34136394, 2021). "Synaptophysin (SYP) gene expression levels correlate with the survival rate of glioma patients." (PMID 34136394, 2021). "In vivo, >10% synaptophysin-positive tumour cells were present in >90% of all gliomas." (PMID 30297697, 2018). "Synaptophysin positivity was detected in 7 high-grade gliomas." (PMID 18398462, 2008). "Moreover, synaptophysin has a limited utility in high-grade gliomas; for example, high-grade gliomas (glioblastomas and anaplastic astrocytomas) often lose synaptophysin expression as they become more undifferentiated, reducing its reliability as a prognostic marker in aggressive gliomas." (PMID 40937216, 2025). "Moreover, multivariate Cox regression revealed that CYBB, CD53, SCRT1 and SYP might be independent factors for predicting the prognosis of gliomas." (PMID 35982398, 2022). "Moreover, further multivariate Cox regression analysis revealed that the expression of CYBB (P = 0.00087), CD53 (P = 0.04883), SCRT1 (P = 0.00071) and SYP (P = 0.02491) can be independent factors of the prognosis of gliomas and predict the survival of glioma patients." (PMID 35982398, 2022). "Therefore, as the most common neural marker, it is worth exploring whether the expressive level of synaptophysin is related to the malignant degree of gliomas and the survival prognosis of patients." (PMID 34136394, 2021). "We identified six hub genes (RAB3A, TYROBP, SYP, CAMK2A, VSIG4, and GABRA1) that predicted the prognosis of glioma." (PMID 36072978, 2022). "Six hub genes related to glioma diagnosis and prognosis were identified, including RAB3A, TYROBP, SYP, CAMK2A, VSIG4, and GABRA1." (PMID 36072978, 2022). "After a series of database screening tests, we identified 11 modules during glioma progression, followed by six hub genes (RAB3A, TYROBP, SYP, CAMK2A, VSIG4, and GABRA1) that can predict the prognosis of glioma and were validated in glioma tissues by qRT-PCR." (PMID 36072978, 2022).
glioma (continued). "In glioma patients, particularly in grade II and grade III patients, the higher the expression level of SYP, the better was the survival rate of the patient." (PMID 34136394, 2021). "To further confirm the presence of synaptophysin-positive glioma cells in vivo, we used a tissue-microarray including three IDH1 positive gliomas." (PMID 30297697, 2018). "Out of eight glioma stem cell (GSC) lines, seven revealed positivity for the synaptic marker protein synaptophysin." (PMID 30297697, 2018). "We also studied the glioma cell multi-lineage differentiation potential in vivo by assessing GFAP and NSE/synaptophysin expression in the corresponding formaldehyde fixed specimens." (PMID 18398462, 2008). "GFAP expression was detected, as anticipated, in all low- and high-grade gliomas analyzed, but the expression of NSE and synaptophysin was only detected in high-grade gliomas." (PMID 18398462, 2008). "To study glioma cell differentiation potential along neuronal lineage, we performed an immunohistochemical staining for pan-neuronal marker NSE and synaptophysin expression in archival specimens." (PMID 18398462, 2008). "Across the range of neural tumors, GFAP, OLIG-2 and MAP-2 are generally expressed by gliomas, while the neuronal marker synaptophysin is not." (PMID 25955030, 2015). "In this study, we investigated the expression of multiple cell surface markers characteristic of glial genesis hierarchy in freshly isolated viable glioma cells as well as the expression of GFAP, NSE and synaptophysin in the fixed specimens from a cohort of low-grade and high-grade glioma patients." (PMID 18398462, 2008). "Therefore, it could be concluded that RAB3A, TYROBP, SYP, CAMK2A, VSIG4, and GABRA1 may play a critical role in glioma by regulating immune cells." (PMID 36072978, 2022). "Parthenolide induced glioma cells to express neuronal markers NeuN, MAP2, SYP, and NEFL, but not astrocyte or oligodendrocyte markers." (PMID 39595109, 2024). "iNHAs overexpressing CCDC88A-ALK or PPP1CB-ALK were tumorigenic in vivo with 100% penetrance, forming glial tumors with a high MIB-1 proliferative index, pseudopalisading necrosis, focal GFAP expression, lack of synaptophysin expression and ALK overexpression." (PMID 31554817, 2019). "In low-grade gliomas, no obvious expression of NSE and synaptophysin was detected, but the cells homogeneously expressed GFAP." (PMID 18398462, 2008).
small cell lung carcinoma (15 papers, 2010 to 2025). Small cell lung cancer (SCLC) is a highly aggressive malignant neoplasm, accounting for 10-15% of lung cancer cases, characterized byrapid growth, and early metastasis. "Neuronal subtypes express neuroendocrine markers such as SOX2 and synaptophysin and require small-cell lung cancer–like chemotherapy regimens." (PMID 40735045, 2025). "In the more common counterpart lung cancer, synaptophysin is expressed in 41–75% of small cell lung carcinoma (SCLC) and 58–85% of large cell neuroendocrine carcinomas (LCNEC)." (PMID 35626098, 2022). "A right supraclavicular, right mammary node, and a right cardiophrenic mass resection was performed and pathology showed small cell lung cancer, synaptophysin positive." (PMID 32560187, 2020). "Both pathological and immunohistochemical examinations (thyroid transcription factor-1, synaptophysin, and chromogranin A staining) led to the diagnosis of ovarian metastasis of small-cell lung carcinoma." (PMID 31218185, 2019). "While other pathological markers, such as synaptophysin and chromogranin, are utilized to diagnose small cell lung cancer, more efforts are needed to differentiate the unique small cell lung cancer patterns that may correlate with treatment response and tumor burden." (PMID 31315252, 2019). "The characteristics of EMT and small cell lung cancer (SCLC) transformation were induced, indicated by an increase in synaptophysin protein." (PMID 37880373, 2023). "Subsequent immunohistochemistry after lobectomy confirmed small cell lung carcinoma (SCLC), insofar as that TTF-1 (thyroid transcription factor-1) evidenced a pulmonary origin and Synaptophysin-staining demonstrated neuroendocrine differentiation." (PMID 32450842, 2020). "Additional IHC work up on the archived bioptic material (TTF1, CK7, CK20, chromogranin, synaptophysin, and CD56) resulted in a diagnosis that was in agreement with the 64 microRNA assay first answer of small cell lung carcinoma." (PMID 23758919, 2013). "In fact, up to two-thirds of small cell lung cancer could provide negative results for the relatively specific NE markers synaptophysin and chromogranin A." (PMID 35626098, 2022).
Hyperglycemia (14 papers, 2013 to 2026). An increased concentration of glucose in the blood. "A decreased expression of synaptophysin in diabetic tissues is supported by the fact that hyperglycemia decreases synaptophysin expression." (PMID 41463007, 2025). "We evaluated the expression of doublecortin and synaptophysin in the peri-infarct zone to study the role of hyperglycemia in neurogenesis and synaptogenesis." (PMID 31315686, 2019). "Critically, db/db mice exhibit severe hyperglycemia much earlier in the lifespan, so the null relationship between blood glucose and hippocampal SYP in normal aging may reflect subthreshold influences arising from smaller magnitude and comparatively later onset of elevated blood glucose." (PMID 38596458, 2024). "Moreover, activation of Toll-like receptor 9 (TLR9) by hyperglycemia mediates oxidative stress and astrocytic dysfunction, leading to reduced TSP-1 secretion and synaptophysin expression." (PMID 34063474, 2021). "In support of this, previous studies from our laboratory also showed that hypo- and hyperglycemia do not affect the levels of the synaptic marker synaptophysin in the brain cortex." (PMID 34948265, 2021). "Additionally, we further explored the role of hyperglycemia in synaptic function and observed that the expression of synaptic function-related proteins (PSD95, synaptophysin, and synapsin-1) in the hippocampus was remarkably suppressed under hyperglycemia." (PMID 32766246, 2020). "Cai and collaborators demonstrated that hyperglycemia and hyperlipidemia induced by obesity might enhance the hippocampal endoplasmic reticulum stress and impair the expression of BDNF and synaptophysin, consequently leading to memory and learning dysfunction in rats." (PMID 36235574, 2022). "In addition, and most importantly, we provide evidence that sitagliptin was able to restore synaptophysin and the other synaptic proteins after several weeks of significant hyperglycemia without any change in systemic blood glucose levels." (PMID 34944588, 2021).
large cell neuroendocrine carcinoma (14 papers, 2011 to 2025). A usually aggressive carcinoma composed of large malignant cells which display neuroendocrine characteristics. "None of the cases analyzed in this study exhibited NE phenotype (small cell or large cell neuroendocrine carcinoma) and stained for NE markers (synaptophysin, chromogranin, and CD56)." (PMID 29156772, 2017). "Additionally, if it is positive for the neuroendocrine markers synaptophysin and chromogranin, it is considered large cell neuroendocrine carcinoma (LCNEC)." (PMID 38168015, 2024). "Moreover, a recent study described a case of NUT carcinoma exhibiting positive synaptophysin expression that was misdiagnosed as a large cell neuroendocrine carcinoma." (PMID 38326851, 2024). "In large-cell neuroendocrine carcinoma, CD56 and SYP demonstrated greater sensitivity than INSM1, whereas CgA showed lower sensitivity." (PMID 39937015, 2025). "Synaptophysin was also performed to exclude large cell neuroendocrine carcinoma, but was negative." (PMID 39584166, 2024).